RORA (RAR related orphan receptor A)
Diseases named in the same sentence as RORA in open-access papers (continued):
Sharing a sentence is not in itself a finding about the gene and the disease.
depression (15 papers, 2010 to 2025). "Both genetic polymorphisms in RORA and alterations in its expression levels have been closely associated with an increased susceptibility to depressive disorders." (PMID 38874508, 2024). "As a core clock protein, functional disruptions in RORα can directly impair the regulation of circadian rhythms, thereby increasing the risk for developing depressive disorders." (PMID 38874508, 2024). "Genetic association studies have identified that RORA is a suggestive gene linked more specifically to the depression facet of neuroticism." (PMID 36672898, 2023). "There are many studies exploring the RORA gene and its relation to circadian rhythm, associated with many psychiatry disorders including major depressive disorder, bipolar disorder, or sleep disturbance disorder." (PMID 35484552, 2022). "As recently demonstrated by multiple studies of animal models, GWA, and linkage studies converging on variants in the RORA gene, it may be linked to bipolar disorder and trait depression." (PMID 36672898, 2023). "Besides, the actual literature describes some of the genes (RORA, Gabrb2, Npas4, and Junb) being associated with depression-like behavior." (PMID 25400562, 2014). "In addition, RORA proteins are involved in protecting neurons and glial cells from oxidative stress-induced apoptosis, which is a potential mechanism implicated in the pathophysiology of depression and anxiety disorders." (PMID 36672898, 2023). "First, it is among the first to systematically investigate the interactive effects of anxiety, depression, and circadian clock gene polymorphisms (CLOCK, PER2, RORA) on sleep disorders in mental workers." (PMID 40951374, 2025). "RORA is involved in the regulation of circadian rhythms, and it has been suggested to be correlated with depression vulnerability." (PMID 35711908, 2022). "The effects of anxiety, depression, and CLOCK, PER2, and RORA gene polymorphisms and their interactions on sleep disorders were further analyzed, to provide scientific references for the reduction of the risk of the occurrence of sleep disorders in mental workers." (PMID 40951374, 2025). "Moreover, the Th17/Treg transcription factor RoRα/FoxP3+ was significantly and negatively correlated with 5-HT contents, while it was positively correlated with depression-like behaviors." (PMID 36430328, 2022). "RORA, a transcription factor that downregulates BDNF, was targeted by hsa-miR-181c-5p and hsa-miR-20a-5p that were correlated with depression and education, respectively." (PMID 36040555, 2022). "Accumulating evidence indicates a role for RORα in several neuropsychiatric disorders, including autism spectrum and bipolar disorder (ASD), schizophrenia, depression, and posttraumatic stress syndrome." (PMID 26878025, 2015). "While SR10067 enhances the depression-like phenotype of naive mice, SR1078, an agonist of RORα/γ35,36, exhibited antidepressant-like effects selectively in our CDM depression model with already dysregulated circadian clock in the mPFC (and no nonspecific effects in naive mice)." (PMID 39179578, 2024). "AHR or RORγt genetic impairment in CD4+T cells does not eliminate depression vulnerability in UCRS mice, whereas neutralization of RORα and RORγt may prevent depression in UCRS rats." (PMID 39655201, 2024).
autoimmune disease (14 papers, 2012 to 2025). A disorder resulting from loss of function or tissue destruction of an organ or multiple organs, arising from humoral or cellular immune responses of the individual to their own tissue constituents. "Aberrant expression of RORα has been associated with autoimmune diseases, neurodegenerative conditions, and metabolic disorders." (PMID 40799648, 2025). "RORα is a member of the ROR family, and its RORα function has been implicated in several pathological processes, such as cancer, autoimmune diseases, inflammation, osteoporosis, and metabolic syndrome." (PMID 26199639, 2015). "Similar to RORγ, besides being a transcription activator of BMAL1, RORα drives Th17 signature genes and, thus, targeting RORα has beneficial effects in autoimmune diseases." (PMID 40131242, 2025). "In systemic lupus erythematosus, another autoimmune disease, melatonin protects endothelial cells via a RORα-dependent mechanism by reducing the expression of inflammatory factors and inhibiting macrophage migration." (PMID 34064466, 2021). "Taken together, these observations suggest that RORα has anti-inflammatory functions in autoimmune diseases, such as RA." (PMID 31636631, 2019). "In addition, SR1001, a high-affinity ligand for RORα and RORγ, was synthesised to effectively alleviate autoimmune diseases and type 1 diabetes by targeting RORα and RORγ to restrain the function of Th17 cells." (PMID 34064466, 2021). "Indeed, Th17 cells are implicated in the development of several autoimmune diseases (e.g., autoimmune arthritis), and mice lacking RORα and RORγ exhibit absence of Th17, and are susceptible to developing autoimmune disorders." (PMID 33717162, 2021). "Melatonin regulates RORα/γ expression through MT1 receptor, and promotes T cell differentiation in autoimmune diseases." (PMID 39522347, 2024). "We recently demonstrated that the Liver X Receptor (LXR) agonist, T0901317 (T09), also displays high-affinity RORα and RORγ inverse activity, potentially explaining its effectiveness in various TH17-mediated autoimmune disease models." (PMID 23029557, 2012).
colon carcinoma (14 papers, 2012 to 2025). "PGE2/PKCα-dependent phosphorylation of RORα can weaken the expression of Wnt target genes in colon cancer cells." (PMID 41425709, 2025). "Colon cancer research has determined that Wnt5a/PKCα-dependent phosphorylation of serine residue 35 of RORα is crucial to link RORα to Wnt/β-catenin signaling." (PMID 33336001, 2020). "The necrosis and apoptosis of cocultured colon cancer cells with T cells were significantly increased upon RORα agonist treatment." (PMID 32610705, 2020). "In colon carcinoma cells, RORα was shown to bind β-catenin directly and inhibit β-catenin-mediated transcriptional activation of the target genes, cyclin D1 (CCND1) and c-myc (MYC), resulting in repression of cell proliferation and migration." (PMID 26878025, 2015). "PGE2/PKCα-dependent phosphorylation of RORα has been reported to attenuate Wnt target gene expression in colon cancer cells, while sumoylation of RORα enhanced its transcriptional activity." (PMID 26878025, 2015). "Downregulation of RORα phosphorylation was observed in colon cancer." (PMID 23443091, 2012). "However, in one report, the production of RORα mRNA in colorectal cancer patients was unchanged, while RORα phosphorylation was found reduced and might be involved in colon cancer progression." (PMID 29904382, 2018). "Melatonin treatment induced apoptosis in the murine colonic cancer; the effect was diminished by RZR/RORα antagonist CGP 55644." (PMID 23443091, 2012). "We demonstrate that RORα/HDAC-mediated attenuation of NF-κB signaling controls the balance of cholesterol metabolism in CD8+ T cells, and that therapeutic strategies targeting this epigenetic regulation could be beneficial to the treatment of solid tumors including colon cancers." (PMID 32610705, 2020).
bipolar disorder (13 papers, 2009 to 2024). A disorder of the brain that causes unusual shifts in mood, energy, activity levels and the ability to carry out day-to-day tasks. "The polymorphisms of gene RORA were associated with bipolar disorders in humans, which are characterized by major disruptions in circadian rhythms, such as abnormal sleep/wake cycles and alternation in appetite rhythm." (PMID 39092175, 2024). "In terms of brain cognitive functions such as mood, the RORA gene was reported to increase the risk of acquiring psychiatric and neurological disorders, including bipolar disorder, autism spectrum disorder, and post-traumatic stress disorder." (PMID 28412756, 2017). "In addition, we found no strong evidence for association between the age-at-onset of bipolar disorder with any RORA or RORB SNPs." (PMID 19909500, 2009). "In addition, genes linked to ID (TCF4, CPLX1, CDK6, KDM5B), ASD (RORA, KDM5B), and bipolar disorder (ZNF804A) were also among the 16 differentially expressed target genes." (PMID 29665782, 2018). "Association studies of NR1D1, RORA, and RORB genes in bipolar disorder." (PMID 25789810, 2015). "Moreover, ARNTL, RORA, RORB and RXRG were associated with bipolar disorder in a meta-analysis integrating data from genome-wide association studies and human and animal model expression studies." (PMID 20195522, 2010). "Of note, both RORB and RORA have nominally suggestive signals in three recently reported genome-wide association studies for bipolar disorder that do not survive correction for multiple comparisons." (PMID 19909500, 2009). "Here we report association studies for RORA and RORB in a pediatric bipolar disorder cohort." (PMID 19909500, 2009). "In addition, other clock genes were associated with these psychiatric disorders, such as Npas2 (winter depression, autism spectrum disorder and schizophrenia), RORA and RORB (bipolar disorder) or Tim, Dbp and Ck1ε (autism spectrum disorder)." (PMID 28468274, 2017).
Hepatic steatosis (13 papers, 2013 to 2025). Steatosis is a term used to denote lipid accumulation within hepatocytes. "Together, we demonstrate that enhanced PPARγ transcriptional activity by RORα deficiency is de-activated by PPARγ antagonism to restore metabolic homeostasis, including body weight gain, hepatic steatosis and glucose and lipid metabolism." (PMID 28757615, 2017). "PPARGC1α has been shown to induce expression of Clock, Bmal1, Rev-erbα, and Rev-erbβ and increase transcriptional activity of RORα, with deficiency of this protein contributing to hepatic steatosis after short-term starvation." (PMID 23951220, 2013). "HFD-fed mice treated with RORα agonist JC1 showed attenuation of hepatic steatosis due to activation of AMPK signaling in the liver." (PMID 35323681, 2022). "Here, we revealed a novel role of RORα in mitochondrial quality control that inhibits further progression of hepatic steatosis to NASH." (PMID 29167529, 2017). "Recently, we demonstrated that RORα has an inhibitory effect on lipid accumulation and oxidative stress, thereby attenuating hepatic steatosis and NASH15,19." (PMID 29167529, 2017). "Recently, two research groups reported a protective role of RORα against hepatic steatosis by employing the liver-specific depletion of RORα or RORα/γ." (PMID 29167529, 2017). "Disrupted PRL rhythm caused by impaired transcriptional regulation of RORα in the pituitary, accompanied by disturbed oscillation of PRL signaling pathway and the resulting heightened lipogenesis in the liver, contributed to SJL-induced fatty liver." (PMID 40462123, 2025). "Lee and colleagues originally reported that RORα attenuates hepatic steatosis by activating AMPK65." (PMID 37653034, 2023). "Recent work has suggested that RORα agonists may be effective in preventing hepatic steatosis, and liver-specific Rorα deletion correspondingly worsens hepatic steatosis." (PMID 32363197, 2020). "Hepatic steatosis was severe in RORα-LKO mice compared with flox/flox (f/f) mice." (PMID 29167529, 2017). "While hepatic gene expression profiles were similar among CD-fed genotypes, hepatic gene expression profiles of lipogenesis, gluconeogenesis, and lipid sequestration in the HFD-fed RORαLKO were largely increased, indicating that RORα protects against HFD-induced hepatic steatosis." (PMID 28757615, 2017). "The CDAA diet produced a massive hepatic steatosis, but RORα deletion in macrophages did not impact on liver weight nor steatosis level." (PMID 33273527, 2020). "Thus, it is highly possible that hepatic steatosis phenotype in HFD-fed RORαLKO mice may be resulted from both upregulated PPARγ activation and suppressed PPARα transcriptional activity in the absence of RORα." (PMID 28757615, 2017).
nonalcoholic steatohepatitis (13 papers, 2017 to 2025). "In nonalcoholic steatohepatitis conditions, RORA induces Kruppel-like factor 4 (KLF4) to promote anti-inflammatory macrophage polarization, thereby ameliorating disease progression." (PMID 40874179, 2025). "Another confirmed receptor for MaR1 is retinoic acid-related orphan receptor α (RORα), which induces nonalcoholic steatohepatitis (NASH) protection through the MaR1/RORα/12-lipoxygenase (12-LOX) autoregulatory circuit." (PMID 35109876, 2022). "An agonist of RORA stimulated lipid metabolism by inducing microRNA-122 expression in a mouse model of nonalcoholic steatohepatitis, which subsequently reduced hepatic lipotoxicity and fibrosis." (PMID 35195816, 2022). "For example, the novel endogenous ligand of RORα, maresin 1, has been identified as a therapeutic agent for non-alcoholic steatohepatitis by activating RORα to regulate hepatic macrophage polarity." (PMID 34064466, 2021). "RORα, a crucial receptor in the cholesterol pathway, is now regarded as an important and promising target in treating many diseases, including nonalcoholic steatohepatitis and cardiac hypertrophy." (PMID 34366712, 2021). "A study in the nonalcoholic steatohepatitis model showed that RORα reduced ROS levels in hepatocytes and suppressed hepatic oxidative stress, which is accompanied with induction SOD2 and Gpx1." (PMID 34639006, 2021). "Lastly, we demonstrate the presence of a novel adaptive macrophage subset with increased RORA gene expression, which has been shown to promote anti-inflammatory polarization of hepatic macrophages in a murine model of nonalcoholic steatohepatitis and a human monocyte cell line." (PMID 33411796, 2021). "Surprisingly, RORα was unchanged in both the high-sugar fed and high-fat mice, which is similar to other reports in rats fed a high-sucrose diet, however these data are in contrast to the observations in human liver biopsies taken from patients with NAFLD and nonalcoholic steatohepatitis (NASH)." (PMID 37642240, 2023).
autism spectrum disorder (11 papers, 2013 to 2023). A spectrum of developmental disorders that includes autism, and Asperger syndrome. "Retinoic acid-related orphan receptor alpha (RORA) has been reported to be suppressed in autistic patients and is associated with autism spectrum disorders (ASD), although the potential role and mechanism of RORA on gastrointestinal (GI) symptoms in ASD patients is still not reported." (PMID 35164690, 2022). "Gene variants of RORA have been linked to autism spectrum disorder (ASD; Akashi & Takumi, 2005)." (PMID 31374129, 2019). "We have recently identified the nuclear hormone receptor RORA (retinoic acid-related orphan receptor-alpha) as a novel candidate gene for autism spectrum disorder (ASD)." (PMID 23697635, 2013). "Our independent cohort studies have consistently shown the reduction of the nuclear receptor RORA (retinoic acid-related orphan receptor-alpha) in lymphoblasts as well as in brain tissues from individuals with autism spectrum disorder (ASD)." (PMID 24119295, 2013). "Reduced levels of the nuclear receptor TF RORA have been observed in the prefrontal cortex and cerebellar neurons of individuals with autism spectrum disorder (ASD), and retinoic acid signaling pathways have been reported to be disrupted in ASD-afflicted individuals." (PMID 36424644, 2022). "It has been reported that hsa-miR-137 could repress RORA in autism spectrum disorders." (PMID 33842355, 2021).
Insulin resistance (11 papers, 2013 to 2025). Increased resistance towards insulin, that is, diminished effectiveness of insulin in reducing blood glucose levels. "Deficiency in RORγ also protects against diet-induced insulin resistance by a mechanism that appears different from that in RORα deficiency." (PMID 23355833, 2013). "Indeed, RORα-deficient staggerer mice are protected against age- and diet-induced obesity, hepatosteatosis and insulin resistance." (PMID 32973801, 2020). "This gene has been implicated in the regulation of obesity and insulin resistance, suggesting that the reduced susceptibility to metabolic syndrome in RORα-deficient mice might at least in part be attributed to Il1rn repression." (PMID 26878025, 2015). "Adipose tissue-associated inflammation, which plays a critical role in the development of insulin resistance, is considerably diminished in RORα-deficient mice as indicated by the reduced infiltration of M1 macrophages and decreased expression of many proinflammatory genes." (PMID 23355833, 2013). "Whether inhibition of Th17 differentiation plays a role in the protection RORα- and RORγ-deficient mice against diet-induced insulin resistance needs further study." (PMID 23355833, 2013). "Altogether, our data strongly demonstrate that hepatic RORα is required for prevention against insulin resistance." (PMID 28757615, 2017). "Attenuating RORα/γ activity by antagonist treatment might also be beneficial for the management of metabolic diseases, including metabolic syndrome and insulin resistance." (PMID 26878025, 2015). "RORα is decreased in liver biopsies taken from patients with NAFLD, and liver-specific RORα knockout mouse models exhibit exacerbated weight gain and insulin resistance." (PMID 37642240, 2023). "In these mice, reduction of RORα expression protected against DIO and improved glucose metabolism and insulin resistance were observed while also decreasing markers of inflammation." (PMID 28744254, 2017).